PFKFB3 (6-phosphofructo-2-kinase/fructose-2,6-biphosphatase 3)
Diseases named in the same sentence as PFKFB3 in open-access papers (continued):
Sharing a sentence is not in itself a finding about the gene and the disease.
cancer (continued). "In studies related to cancer and aerobic glycolysis, the interaction between HIF-1α and PFKFB3 gene expression has been found to affect glycolysis progression and cell activity." (PMID 38264652, 2023). "Pathway activity analysis showed that PFKFB3 correlated top 6 genes mainly activate EMT, RAS/MAPK, and RTK pathway, and inhibit cell cycle and DNA damage response in pan-cancer." (PMID 37253634, 2023). "The results showed that ENO1, PFKFB3, NSDHL and SQLE were primarily detected in the in the cytoplasm of cancer cells in HNSCC tissues and the expression of these protein in recurrent HNSCC was significantly higher than that in normal tissues." (PMID 36841765, 2023). "Firstly, the direct inhibition of PFKFB3 emerges as a key regulator of mTORC1 activity and a promising target in MCL-1-dependent cancers." (PMID 37684238, 2023). "The 6-phosphofructo-2-kinase/fructose-2,6-bisphosphatase 3 (PFK-2/FBPase-2, PFKFB3) is a glycolysis regulatory enzyme and plays a key role in oncogenesis of several cancers." (PMID 37253634, 2023). "In this study, we conducted a comprehensive analysis of the relationship between PFKFB3 expression, patient prognostic, TMB, MSI, MMR, and especially TME in pan-cancer base on TCGA and GEO databases." (PMID 37253634, 2023). "Our analyzed data confirmed the possible effect of PFKFB3 in cell cycle progression and migration as well as the effect of PFKFB4 in cancer stemness in OSCC." (PMID 37919747, 2023). "In this study, we conducted a comprehensive assessment of the relationship between PFKFB3 expression, patient prognosis, and especially TME in cancers based on the TCGA database." (PMID 37253634, 2023). "Our data showed that PFKFB3 and PFKFB4 play different roles; PFKFB3 is involved in cell viability, G2/M cell cycle progression, invasion, and migration, whereas PFKFB4 is involved in the drug resistance and cancer stemness of OSCC cells." (PMID 37919747, 2023). "PFKFB3 and PFKFB4 are the most overexpressed and active isoforms in a plethora of cancers; these two isoforms are responsible for the common upregulation of F-2,6-BP seen in cancer cells." (PMID 38201444, 2023). "We also observed that PFKFB3 and PGC1A values correlated significantly and positively only in carcinoma samples; however, the differences were not significant between the groups (p = 0.18)." (PMID 37047426, 2023). "We found a significant difference for the PFKFB3/PRDX3 correlation, with PFKFB3/PRDX3 values higher in the carcinoma group." (PMID 37047426, 2023). "We found that PFK158 treatment and PFKFB3 knockdown enhanced the ABCG2-interacting drugs doxorubicin, etoposide, and 5-fluorouracil in reducing cell viability under conditions of enriched cancer stem cells (CSC)." (PMID 35804016, 2022). "Therefore, PFKFB3 inhibition may be a promising approach for cancer treatment." (PMID 35209949, 2022). "PFKFB3 is a member of the 6-phosphofructo-2-kinase/fructose-2,6-bisphosphatases (PFKFB) family and is closely related to many aspects of cancer including cell proliferation, vessel aggressiveness, drug resistance and TME." (PMID 36071839, 2022). "KAN is the latest inhibitor of selective metabolic kinase PFKFB3, more effective than PFK15, that has been identified as a potential cancer treatment strategy." (PMID 36187335, 2022). "In cancer, VEGF stimulates PFKFB3 expression and promotes directional migration and filopodia/lamellipodia formation in ECs." (PMID 33671514, 2021). "For example, phosphorylation of PFKFB3 at Ser461 by AMPK increases glycolytic flux and promotes cancer cell proliferation." (PMID 34079757, 2021). "This revealed a set of genes shared with human eTreg cells from affected sites in JIA, RA, and cancer including BATF, VDR, MICAL2, TOX2, KAT2B, PFKFB3, and IL12Rβ2." (PMID 33976194, 2021).
cancer (continued). "PFKFB3 and PFKFB4 stimulate glucose uptake and boost glycolytic flux to cancer cells by increasing F-2,6-BP, which is a compound promoting glucose utilization by glycolysis." (PMID 33671514, 2021). "By downregulating PFKFB3 expression, TTP inhibits energy production and glycolytic flux in cancer cells, increases glutathione expression, and controls the balance between glycolysis and the pentose phosphate pathway at the post-transcriptional level." (PMID 34026612, 2021). "As such, PFKFB3 is essential in the DDR pathway, a commonly over-efficient process in treatment-resistant cancers." (PMID 34831136, 2021). "Analogously to what occurs in cancer cells, the expression of TIGAR and PFKFB3 allows for a high glycolytic flux together with increased capacity for DNA synthesis and control ROS levels in activated lymphocytes." (PMID 34299056, 2021). "Overall, these studies strongly indicate a role of PFKFB3 and PFKFB4 in the invasiveness of cancer cells." (PMID 33671514, 2021). "PFKFB3, also regulated by HIF-1α, was reported to be upregulated in multiple cancer types, where it was required for their survival and growth." (PMID 34683117, 2021). "Glycolysis regulatory enzymes such as phosphofructokinase 2(PFK2) increase glycolysis flux by activating PFK1, whose subtype PFKFB3, which is expressed in many cancers, is a key rate-limiting enzyme that controls glycolysis." (PMID 34922556, 2021). "6-Phosphofructo-2-kinase/fructose-2,6-bisphosphatase-3 (PFKFB3) is an enzyme that controls the level of fructose-2,6-bisphosphate and is crucial in BC cancer progression." (PMID 32806533, 2020). "For example, targeting the glycolytic enzymes PFKFB3 and PKM2 which are highly expressed in cancer cells compared to normal cells, would provide a novel means of targeting Ca2+ pumps specifically in cancer cells." (PMID 33282859, 2020). "Recent studies suggest that metabolic isoenzymes of phosphofructokinase II (PFK-II) – PFKFB3 and PFKFB4, often induced in hypoxic environment, significantly contribute to enhancement of glucose metabolism and in consequence cancer progression." (PMID 31754349, 2019). "In fact, studies in recent years revealed that PFKFB3/PFKFB4 isoenzymes are excellent candidates for glycolysis targeting, especially in cancer cells." (PMID 31754349, 2019). "Several in vitro studies revealed that targeting PFKFB3 and PFKFB4 in cancer cells results in glycolysis inhibition and in consequence, attenuation of tumor growth." (PMID 31754349, 2019). "Initially, using the R2 data base we analyzed the relation between PFKFB3 and PFKFB4 expression and the overall survival rate in the panel of cancers." (PMID 31754349, 2019). "In this sense, targeting of both PFKFB3 and PFKFB4 isoenzymes has been proposed to be advantageous due to their high expression in some cancer cells." (PMID 30234009, 2018). "In the present study, we found that PFKFB3 was mainly located in the nucleus and less so in cytoplasm in HCC cells; several other studies reported similar findings for other types of cancer cells." (PMID 29559632, 2018). "However, the therapeutic effects of PFKFB3 suppression targeting cancer metastasis remain unknown." (PMID 28061878, 2017). "PFKFB3 was an important glycolytic activator and active PFKFB3 induced PFK1 activity and led to glycolysis in cancer cells." (PMID 27884166, 2016). "Thus, timed PFKFB3 inhibition could improve the efficacy of anti-cancer therapy." (PMID 27079271, 2016). "Considering the stimulatory effect of CLOCK on PFKFB3 expression, it is likely that 3PO treatment also acted through reducing CLOCK expression to decrease PFKFB3 expression, thereby amplifying its anti-cancer effect." (PMID 27079271, 2016).
cancer (continued). "In this work we studied two glycolysis-related enzymes, PFKFB3 and PFK1, in distinct cellular systems (iPSs, cancer cells, CSCs and fibroblasts) in order to capture differences in cell cycle regulation and metabolic activity." (PMID 26337471, 2015). "We examined the effect of hypoxia on PFKFB3 and PFK1 gene and protein expression in cancer-, CS-, iPS cells and fibroblasts." (PMID 26337471, 2015). "PFKFB3 and PDHK1 were up-regulated under hypoxic conditions in both cancer cell lines, while Hexokinase II and LDHA were up-regulated only in MCF-7 cells at 0.5% O2." (PMID 26259240, 2015). "When tested on cultured cancer cells, both N4A and YN1 inhibited PFKFB3, suppressing the Fru-2,6-BP level, which in turn suppressed glycolysis and, ultimately, led to cell death." (PMID 21957443, 2011). "Although N4A and YN1 show comparatively selective PFKFB3 inhibition between the PFKFB isoforms, the anti-proliferative effect of the inhibitors on cancer cells cannot be solely ascribed to the inhibition of PFKFB3 kinase activity." (PMID 21957443, 2011). "Furthermore, pharmacological inhibition of PFKFB3 by KAN0438757 impairs deoxynucleotide synthesis required for DNA repair, thereby compromising the survival of cancer cells exposed to radiation-induced DNA damage." (PMID 41296396, 2025). "Mechanically, we found that TZP exerted its anti‐CRC effect by inhibiting glucose influx and targeting HIF‐1α for degradation with reduced expression of its downstream glycolytic gene PFKFB3 and PFK‐1, leading to reduced glycolysis and TCA in the cancer tissues." (PMID 40125821, 2025). "–38 Building on evidence that hyperosmotic environments activate PFKFB3 transcription in cancer cells, we hypothesized that hyperosmotic stress in DED may drive NF-κB–mediated inflammatory cascades via PFKFB3-dependent glycolytic reprogramming." (PMID 40879294, 2025). "Although PFKFB3 is not directly involved in glycolysis, PFKFB3 inhibition reduces lactate production and proliferation in several cancer cell lines." (PMID 41235226, 2025). "HK2, PFKFB3, and PKM2 have been identified as key glycolysis enzymes that participate in glucose metabolism; they can enhance glucose uptake and lactate production, thereby providing a source of energy for cancer cells." (PMID 39684424, 2024). "Also, in cancer cells and HCC cells, the PFKFB3 gene was found to play a significant role in the activation of glycolysis." (PMID 39767591, 2024). "6-Phosphofructokinase-2/fructose-2,6-bisphosphatase 3 (6-phosphofructokinase-2/fructose-2,6-bisphosphatase 3, PFKFB3) can phosphorylate fructose 6-phosphate to fructose-2,6-bisphosphate, which in turn activates PFK1 and increases glycolytic flux in cancer cells." (PMID 39496001, 2024). "PFKFB3 was upregulated in PC12 cells because they are proliferating cancer cells, whereas in the brain, PFKFB3 is abundantly expressed in astrocytes but is not typically found in neurons." (PMID 37108268, 2023). "The expression of PFKFB2, PFKFB3, and PFKFB4 has been observed in several types of cancers." (PMID 37919747, 2023). "However, the systematic study of crosstalk between PFKFB3 and TME in pan-cancer has less been examined." (PMID 37253634, 2023). "Furthermore, PFKFB3 is involved in the growth and metastasis of OSCC cells, but PFKFB4 is involved in chemoresistance and the cancer stemness of OSCC cells." (PMID 37919747, 2023). "In addition, overexpression of TIGAR in cancer cells induces a glycolytic phenotype in CAFs and promotes the expression of HIF-1 α, PFKFB3 (6-phosphofructo-2-kinase/fructose-2,6-biphosphatase 3) and lactate dehydrogenase-A along with increasing glucose uptake." (PMID 37065872, 2023). "PFKFB3 is the most expressed PFKFB family gene in proliferating cells and cancer cells." (PMID 36973739, 2023). "Our results demonstrate that PFKFB3 is involved in cell growth by regulating G2/M cell cycle progression and migration but not in chemoresistance and cancer stemness in OSCC cells." (PMID 37919747, 2023).
cancer (continued). "For group 1, seven of the thirteen novel-loci-related coding or noncoding genes, namely F11/F11-AS1, PFKFB3, PRMT8, FAM66C, NAV2/NAV2-AS1, FRMD4A, and KIAA0232, have been demonstrated to be correlated with the development of HCC or other cancers in many studies." (PMID 38003606, 2023). "There was an upregulation of genes participating in glucose transport, mainly GLUT6, the glycolytic enzymes HK1 and HK2, the phosphofructokinase PFKFB3, the enolases ENO3, and ENO2, and the lactate dehydrogenase LDHA, similar to the Warburg effect in cancer cells." (PMID 35163725, 2022). "Awaiting the development of non-toxic inhibitors of PFK1 and PFKFB3, we will emphasize how in cultured cancer cells of diverse origins, the targeting of PFK1 has been achieved by the administration of high dosages of citrate, a physiologic inhibitor of PFK1." (PMID 35626081, 2022). "PFKFB3 phosphorylates fructose-6-phosphate (F-6-P) to fructose-2,6-bisphosphate (F-2,6-BP), which subsequently allosterically activates phosphofructokinase-1 (PFK1) and stimulates high glycolytic flux in human cancers." (PMID 35209949, 2022). "Following promising inhibition of cancer stemness and ABCG2 levels, an impact of PFKFB3 depletion by PFK158 or its genetic KD effect on migration and invasion was examined on H1048 and H1882 cells through invasion and migration assay and EMT protein expression analysis by immunoblot." (PMID 35804016, 2022). "Awaiting the development of specific and non-toxic inhibitors of PFK1 and PFKFB3, we propose to test strategies increasing the citrate level in cancer cells, since citrate is a well-known physiologic and potent inhibitor of PFK1 and PFK2." (PMID 35626081, 2022). "It was found that LncRNAs can also control cancer cell metabolism, viz., lncRNA YIYA regulates CDK6 (cell division protein kinase 6) dependent phosphorylation of PFKFB3 (fructose bis-phosphatase PFK2), and thus can convert glucose 6-phosphate (G6P) to fructose-2,6-phosphate." (PMID 36685962, 2022). "Similarly, PFKFB3, a direct target of HIF1, is upregulated in all groups in comparison to group 1 and regulates glucose metabolism and promotes cancer progression and growth." (PMID 35568708, 2022). "However, most recent studies have focused on an increased expression of PFKFB3 and PFKFB4 in cancer tissues and their role in carcinogenesis." (PMID 33671514, 2021). "PFKFB3 and PFKFB4 affect carcinogenesis and cancer metabolism in a multidirectional manner." (PMID 33671514, 2021). "In different cancer cell types, GIT1, S6K1, and PFKFB3 have been identified as targets of PKD3." (PMID 34145024, 2021). "PFKFB3 and PFKFB4 are the two primary isoenzymes overexpressed in various kinds of human cancers." (PMID 34211613, 2021). "Furthermore, lower PFKFB3 and PFK-I expression levels have been demonstrated in induced pluripotent stem (iPS) cells compared to cancer and cancer stem cells (CSCs)." (PMID 33671514, 2021). "Inhibition of glycolysis enzyme, such as hexokinase 2 (HK2) 11-13, 6-phosphofructo-2-kinase/fructose-2, 6-bisphosphatase 3 (PFKFB3) 14 and pyruvate kinase M2 (PKM2) 15, results in reduced cancer cell invasion and metastasis, indicating the critical role of glycolysis in these biological events." (PMID 33897890, 2021). "The isoform PFKFB3 favours the formation of F26BP and is an anti-cancer drug target." (PMID 33141153, 2020). "PFKFB3, GLUT1, and c-Myc were reported to maintain stemness features in cancer at certain levels." (PMID 33256802, 2020). "Analysis of cancer samples reveals intriguing parallels between PFK-P and PKM2 (pyruvate kinase M2), and simultaneous increases in PFK-P and PFKFB3 (responsible for F26BP production) transcript levels, suggesting prioritisation of metabolic flexibility in cancers." (PMID 33141153, 2020).
cancer (continued). "Amongst these PFKFB3 inhibitors, 3PO and its derivative PFK158 have been reported to reduce the cellular levels of F2,6BP, inhibit glucose uptake and lactate production, thus facilitating apoptosis in cancer cells." (PMID 31406177, 2019). "Suppressing glycolysis by selective inhibition of PFKFB3 isozyme is considered to be a promising therapeutic target due to its strong allosteric activity towards PFK1, which stimulates glycolysis and often overexpressed in most of the cancers." (PMID 31562297, 2019). "Firstly, PFKFB3 was widely expressed in several cancer types, and we here confirmed the high expression of PFKFB3 in HNSCC tissues but not in the adjacent normal tissues." (PMID 28061878, 2017). "Here, we have reviewed the biological characteristics of PFKFB3, the regulation pathway of glucose metabolism manipulated by PFKFB3, and other regulatory mechanisms in hematologic and non-hematologic malignant tumor cells." (PMID 28977989, 2017). "The modulation of the drug targets was examined under these varying oxygen conditions and of the five targets examined, PFKFB3 and PDHK1 were up-regulated under hypoxic conditions in both cancer cell lines, while Hexokinase II and LDHA were up-regulated only in MCDF-7 cells at 0.5% O2." (PMID 26259240, 2015). "Unlike cancer cells and iPS, fibroblasts were unaffected by 3PO treatment, which was similar to a previous report showing that transformed fibroblasts (PFKFB3+/−) are more sensitive to this inhibitor than wild-type control fibroblasts (PFKFB3+/+)." (PMID 26337471, 2015). "Furthermore, the analyses of PFKFB3 and PFK1 mRNA expression present an interesting pattern in cancer cells and cancer cell-derived CSCs." (PMID 26337471, 2015). "Importantly, a novel family of related small molecule antagonists of the kinase domain of PFKFB3 (i.e. 3PO, PFK15 and PFK158) have been found to reduce glycolytic flux, ATP and cancer cell viability." (PMID 25115398, 2014). "Strategies to inhibit PFK-2 activity, in particular for PFKFB3, may be successful in reducing the high glycolytic activity of cancer cells." (PMID 24280138, 2013). "Additionally, glutamine deprivation or GLS1 inhibition represses glycolysis and lactate production in several cancer cells through upregulation of thioredoxin interacting protein (TXNIP) and phosphorylation of PFKFB3, potentially reducing lactate-induced differentiation of M2 macrophages." (PMID 41235226, 2025). "In addition to this, overexpression of PFKFB3 increases proliferation of cancer cells, without affecting glucose metabolism." (PMID 40022029, 2025). "Several studies revealed that targeting PFKFB3 and PFKFB4 could inhibit glycolysis in cancer cells." (PMID 37919747, 2023). "Thus, the therapeutic implications of targeting PFKFB3 and PFKFB4 could disrupt glycolysis or Warburg effect and eliminate other signaling mechanisms for cancer progression." (PMID 37919747, 2023). "PFKFB3 is highly expressed in many cancer cells and proliferating non-cancer cells." (PMID 37162556, 2023). "Elevated glucose metabolism, hypoxia-induced GLUT, LDH-A, and PFKFB3 overexpression, and the AKT- and c-Myc-mediated transcriptional activation of HK2 are observed in most cancer cells, and these metabolic changes may be exploited for developing effective therapeutic approaches." (PMID 36768924, 2023). "Consequently, our findings uncover PFKFB3 inhibition as an Ca2+-independent mechanism through which BAPTAi impairs cellular metabolism and ultimately compromises the survival of MCL-1-dependent cancer cells." (PMID 37684238, 2023). "In this regard, some regulatory enzymes, including GLUTs, Hexokinase II (HKII), 6-Phosphofructo-2-kinase (PFKFB3), pyruvate dehydrogenase (PDH), lactate dehydrogenase A (LDHA) and pyruvate kinase M2 (PKM2), should be upregulated to accelerate the rate of glycolysis in cancer cells." (PMID 36230935, 2022).